EGR1 (early growth response 1)
Diseases named in the same sentence as EGR1 in open-access papers (continued):
Sharing a sentence is not in itself a finding about the gene and the disease.
myocardial ischemia (21 papers, 2009 to 2025). A disorder of cardiac function caused by insufficient blood flow to the muscle tissue of the heart. "Early growth response-1 (Egr-1), a transcription factor which often underlies the molecular basis of myocardial ischemia/reperfusion (I/R) injury, and oxidative stress, is key to myocardial I/R injury." (PMID 29422863, 2018). "Thus, our findings suggest that ERK1/2 is an important upstream signal for modulating Egr-1 expression underlying myocardial ischemia stress." (PMID 24883066, 2014). "As a master regulator and transcriptional sensor in vascular dysfunction, EGR1 is functionally activated by hypertrophy, myocardial ischemia/reperfusion, and other related cardiac stress, modulated by its corepressor NAB1." (PMID 40145839, 2025). "EGR1 transcriptionally regulated the expression of mTORC1 and Kir2.1 in myocardial ischemia/reperfusion (I/R) injury." (PMID 37498303, 2023). "Inhibition of ERK1/2 kinase expression downregulates EGR1 expression, thereby reducing myocardial ischemia-reperfusion induced apoptosis and autophagy." (PMID 36687680, 2022). "Up-regulated FGF2/an early growth response protein 1(EGR1) ameliorated cardiac ischemia and systolic dysfunction." (PMID 29755358, 2018). "This can also include DNAzymes targeting EGR1, which have been used by ourselves and others in a range of local delivery models to reduce post-angioplasty restenosis, in-stent restenosis and to lower infarct size following myocardial ischemia-reperfusion." (PMID 39619154, 2024). "However, in a model of myocardial ischemia-reperfusion injury, remote ischemic preconditioning was found to improve myocardial ischemia-reperfusion injury, through the protective role of Egr1 against apoptosis via the Jak-Stat pathway." (PMID 35799890, 2022). "Endothelium dysfunction induced by reactive oxygen species (ROS) is an important initial event at the onset of myocardial ischemia/reperfusion in which the Egr-1 transcription factor often serves as a master switch for various damage pathways following reperfusion injury." (PMID 28111550, 2016). "Reactive oxygen species (ROS)-induced oxidative stress in cells is an important pathophysiological process during myocardial ischemia/reperfusion (I/R) injury, and the transcription factor Egr-1 is a master switch for various damage pathways during reperfusion injury." (PMID 26134032, 2015). "During myocardial ischemia or reperfusion, the expression of many genes such as c-fos, c-jun, junB, Egr-1, and HSP70 is upregulated, and some of them are considered to be involved in the endogenous cardioprotection against myocardial ischemia/reperfusion injury." (PMID 25397408, 2014). "During myocardial ischemia or reperfusion, many genes such as c-fos, c-jun, junB, Egr-1, HSP70 can be up-regulated, and some of these myocardial genes have been considered to be involved in the endogenous cardioprotection against myocardial ischemia-reperfusion injury." (PMID 19333417, 2009).
Anxiety (19 papers, 2012 to 2025). Intense feelings of nervousness, tension, or panic often arise in response to interpersonal stresses. "Egr1 is also involved in the stress response and has been implicated in various stress-related disorders, including depression and anxiety." (PMID 37928724, 2023). "Moreover, Egr1 expression in the rat prefrontal cortex has been implicated in controlling gender differences in social anxiety behaviors." (PMID 35980567, 2024). "Combined with the specific roles of EGR1 in regulating neuronal plasticity (see “EGR1 Role in Pathological States” Section), this provides unique opportunities to investigate the neuronal ensembles underlying anxiety, stress response, and stress-related disorders." (PMID 28321184, 2017). "While effects of Egr1 overexpression likely result from its cumulative impact on gene expression, we identified several anxiety-relevant example genes with expression patterns that are concordant with Egr1’s behavioural effects." (PMID 41390827, 2025). "Egr1 complete knockout mice demonstrate decreased depressive or anxiety-like behavior and impaired performance in spatial learning and memory." (PMID 37928724, 2023). "When determined during adulthood, alcohol withdrawal increased Egr1 induction within the AcbSh of both adult- and adolescent-onset drinking mice, coinciding with the presence of hyper-anxiety." (PMID 30483137, 2018). "Previous studies with Egr-1−/− mice reported normal, or only slight immobility in the open field test, which was attributed to increased anxiety levels." (PMID 28824419, 2017). "In line with these clinical observations, Egr1 mRNA levels are generally found down-regulated in specific brain areas in animal models inducing depressive- and anxiety-like states." (PMID 28321184, 2017). "Since then, the role of EGR1 in regulating anxiety has been further described and targeted to the mPFC, although other structures such as the amygdala or ventral HPC are likely to contribute." (PMID 28321184, 2017). "We found that the cocaine CPP-induced EGR1 activation in the accumbens corridor in CD1 mice bred for normal or high anxiety-related behavior is mediated by D1- and D2-medium spiny neurons." (PMID 25566008, 2014). "In Braf mutants, that exhibit reduced levels of Egr1 mRNA, a similar effect was found in the two anxiety-related behavior tests." (PMID 22529971, 2012). "In addition, studies have shown that after social isolation stimulation, the expression of EGR1 in the hippocampus and hypothalamus of male mice also decreased significantly and showed more anxiety behavior." (PMID 41007965, 2025). "Together, these data identify that neuron-selective deletion of Egr1 within sex did not alter anxiety associated behavior, although it did alter the relationship between activity levels and anxiety between the sexes." (PMID 37928724, 2023). "Therefore, the increased Egr1 expression observed in alcohol-withdrawn mice herein is likely functionally related to the increase in anxiety-related behaviors." (PMID 30483137, 2018). "In line with this hypothesis, we previously reported that the expression levels of the immediate early gene early growth response 1 (Egr1) in the rat mPFC control sex differences in social anxiety behaviors." (PMID 26628058, 2015). "As such, the preponderant regulations, supported by 64.7 % of all DEG, corresponded to a proestrus-specific enrichment of synapse-related genes, partly under the direct transcriptional control of the immediate early gene Egr1, a known mediator of sex differences in anxiety-like behaviors." (PMID 26628058, 2015). "Furthermore, transcription factor EGR1 has been shown to be related to the long-term fear memory and anxiety; our brain datasets unbiasedly identified EGR1 enrichment in the amygdala and hippocampus (the main brain areas for memory formation and storage), thus further validated previous findings." (PMID 34108989, 2021).
Anxiety (continued). "It was shown that in the hippocampus of mice, EGR1 directly interacts with lysine-specific demethylase 1 (LSD1), allowing a permissive chromatin state, and upon stress, this leads to increased Egr1 expression and a high-anxiety phenotype." (PMID 32748368, 2020). "Similarly, the reduction of Egr1 levels by LSD1 knockout, which promotes repressive chromatin state, leads to a low-anxiety phenotype." (PMID 32748368, 2020). "This suggested that these neuron types were not involved in mediating cocaine CPP-induced EGR1 expression and were not affected by high anxiety-related behavior." (PMID 25566008, 2014). "This may account for higher male baseline expression of genes such as Atp1a2, Ppp3r1, and Nrn1, and a lack of an Egr1 effect on the expression of these genes and related phenotypes, such as anxiety-related behaviour, due to a possible ceiling effect in males." (PMID 41390827, 2025).
pancreatic cancer (18 papers, 2012 to 2025). "It has also been reported that δ-tocotrinol in pancreatic cancer cells stimulates the expression of EGR1, which causes apoptosis of pancreatic cancer cells." (PMID 38324544, 2024). "The purpose of this research was to investigate the potential mechanisms by which EGR1 associates with MDR1 to regulate gemcitabine resistance in pancreatic cancer cells." (PMID 38408959, 2024). "Ionizing radiation treatment of PANC1 pancreatic carcinoma cells determined an increase in Egr1 (Early Growth Response Protein 1), which in turn caused repression of heparanase transcription." (PMID 34249755, 2021). "Importantly, both Egr-1 and Ier5 were recently identified as cachexia-associated genes upregulated in muscles of pancreatic cancer patients together with Foxo1." (PMID 25539728, 2014). "Collectively, these results suggest that YAP1 binds to KLF5 and promotes the growth of pancreatic cancer cells, independent of TEAD and TAZ, and also indicate that ATF5 enhances the growth of pancreatic cancer cells by suppressing EGR1 expression." (PMID 40124511, 2025). "EGR1 acts as a pro-metastatic factor in pancreatic cancer cells, promoting cell migration and invasion through the SNAI2–EMT pathway." (PMID 41048344, 2025). "Nonetheless, these results need to be further investigated on a larger scale to demonstrate that EGR1 expression can be used as a valid biomarker to evaluate treatment progression in patients with pancreatic cancer." (PMID 38408959, 2024). "The following in vitro and in vivo techniques were used in this research to explore the potential mechanisms by which EGR1 binds to MDR1 to regulate gemcitabine resistance in pancreatic cancer cells." (PMID 38408959, 2024). "The role and mechanism of EGR1 in pancreatic cancer cell lines can be further explored in the future, providing a new angle for the development of strategies for selective modulators of gene expression." (PMID 38408959, 2024). "We revealed that EGR1 expression was increased in different pancreatic cancer cell lines compared to normal pancreatic ductal epithelial cells." (PMID 38408959, 2024). "In summary, EGR1 knockdown promotes apoptosis and inhibits gemcitabine resistance in pancreatic cancer cells." (PMID 38408959, 2024). "Firstly, we assessed the expression of EGR1 in pancreatic cancer and normal pancreatic tissues from TCGA and GTEx databases, which showed that EGR1 expression levels were significantly higher in pancreatic cancer." (PMID 38408959, 2024). "In our current study, we firstly reported the evidence that EGR1 promoted pancreatic cancer migration and invasion." (PMID 36932397, 2023). "Further, a Tissue Microarray (TMA) was performed to investigate the relationship between EGR1 protein expression and the clinicopathological characteristics of patients with pancreatic cancer." (PMID 36932397, 2023). "Further, the migration and invasion ability of pancreatic cancer cells were detected after knockdown or overexpression of EGR1." (PMID 36932397, 2023). "In this research, we revealed that EGR1 promoted pancreatic cancer metastasis both in vitro and in vivo." (PMID 36932397, 2023). "The IHC staining indicated excessive EGR1 expression in pancreatic cancer tissues compared with paired adjacent normal pancreatic tissues." (PMID 36932397, 2023). "Our findings implied the EMT-promoting effect of EGR1 in pancreatic cancer and revealed the intrinsic mechanism." (PMID 36932397, 2023). "Tissue microarray analysis and immunohistochemistry assays were used to compare the expression of EGR1 in pancreatic cancer and normal pancreatic tissues." (PMID 36932397, 2023). "In the present study, we identified EGR1 as a pro-metastasis factor in pancreatic cancer cells, which promoted cell migration and invasion via the SNAI2-EMT pathway." (PMID 36932397, 2023).
pancreatic cancer (continued). "In pancreatic cancer cells, δ-tocoptrienol triggers the EGR1 expression through the JNK/cJUN pathway, and the upregulated EGR1 binds to the BAX promoter to activate BAX expression, leading to pancreatic cancer cell apoptosis." (PMID 35727266, 2022). "In pancreatic cancer cells, δ-tocotrienol triggers EGR1 expression via the JNK–c-Jun pathway, and the upregulated EGR1 binds to the BAX promoter to initiate the expression of BAX, which causes apoptosis of pancreatic cancer cells." (PMID 33842351, 2021). "Considering EGR-1 has previously been shown to induce apoptosis in pancreatic cancer, EGR-1 was chosen for further validation at the protein level to determine if this change in gene expression resulted in a functional effect." (PMID 30004416, 2018). "The BAX gene, a member of the Bcl-2 apoptotic protein family with pro-apoptotic activity, has previously been shown to be a direct target of EGR1, which subsequently led to apoptosis induction in pancreatic cancer cells." (PMID 29719592, 2018). "EGR1 has been shown to act as a pro-apoptotic factor in pancreatic cancer cells through direct induction of BAX." (PMID 29719592, 2018). "In a pancreatic cancer model, tolfenamic acid-induced Egr1 expression appears to have an essential role in the activation of apoptosis." (PMID 26739353, 2016). "Western blots of xenograft tissues suggested that chronic nicotine induced while GABA inhibited MMP-9, MMP-2 and EGR-1 in pancreatic cancer." (PMID 25260978, 2014). "Immunoblotting detection revealed significantly higher levels (median rate 10.3, P≤0.005, Student’s t-test) of Egr-1 expression in all wasted patients with pancreatic cancer compared with controls." (PMID 22721276, 2012). "In addition, EGR1 is also essential for inducing cell death in pancreatic cancer cells via drug treatment." (PMID 40124511, 2025). "For instance, EGR1 increased pancreatic cancer’s liver metastasis through the P300/SNAI2 pathway." (PMID 39866235, 2025). "Targeting EGR1 may be a novel therapeutic strategy for pancreatic cancer to overcome gemcitabine resistance mediated by MDR1." (PMID 38408959, 2024). "Our study suggests that EGR1 may be involved in the regulation of MDR1 to enhance gemcitabine resistance in pancreatic cancer cells." (PMID 38408959, 2024). "we found that the value of IC50 became lower by silencing EGR1 expression and elevated by overexpressing EGR1.Then, we further investigated whether EGR1 affects Gemcitabine-induced apoptosis in pancreatic cancer cells." (PMID 38408959, 2024). "Besides, EGR1 was positively correlated with EMT process in pancreatic cancer, via a SNAI2-dependent pathway." (PMID 36932397, 2023). "Finally, immunohistochemistry and Western immunoblotting analysis confirmed the strong correlation of Egr-1 within the skeletal muscle of pancreatic cancer patients in response to cachexia." (PMID 22721276, 2012). "EGR1 could be a novel therapeutic target to overcome gemcitabine resistance in pancreatic cancer." (PMID 38408959, 2024). "Finally, in vivo experiments also proved that EGR1 promoted liver metastasis of pancreatic cancer." (PMID 36932397, 2023). "Thus, we wondered whether p300/CBP was involve in the transcription regulation of EGR1 on the SNAI2 promoter in pancreatic cancer." (PMID 36932397, 2023). "Blocking the expression of EGR1 may be a new anticancer strategy for pancreatic cancer." (PMID 36932397, 2023). "In this research, we investigated the interaction between EGR1 and MDR1, hoping to bring new evidence for chemotherapy of pancreatic cancer." (PMID 38408959, 2024). "Notably, EGR1 silencing inhibited pancreatic cancer cell growth and promoted apoptosis.The conclusion that EGR1 expression may affect the sensitivity of pancreatic cancer to gemcitabine provides a new solution for the clinical reduction of drug resistance in pancreatic cancer." (PMID 38408959, 2024).
pancreatic cancer (continued). "In order to further verified the role of EGR1 in pancreatic cancer in vivo, normal control PANC1 cells and stable EGR1-overexpressed PANC1 cells were injected into the spleen of nude mice." (PMID 36932397, 2023). "Thus, we wondered whether EGR1 was involved in the EMT process in pancreatic cancer." (PMID 36932397, 2023). "We further analyzed the expression of ATF5 and EGR1 in mouse pancreatic cancer tissues treated with or without AM80, which reduces tissue stiffness by increasing the number of meflin-positive cancer-restraining CAFs." (PMID 40124511, 2025). "The overexpression of Early growth response 1(EGR1) in pancreatic ductal adenocarcinoma as a mechanism of gemcitabine chemoresistance in pancreatic cancer has not been explored." (PMID 38408959, 2024). "Furthermore, we examined the expression of EGR1 protein and mRNA in human normal pancreatic ductal epithelial cells (HPDE6-C7) and four pancreatic cancer cell lines (BxPC-3, PANC-1, CFPAC-1, and AsPC-1)." (PMID 38408959, 2024). "Additionally, Egr-1 has been found to influence the expression of BAX and BCL2 in pancreatic cancer cells, with an increase in BAX and a decrease in BCL2 observed in multiple experimental conditions." (PMID 37046823, 2023). "The results showed that EGR1 was highly expressed in pancreatic cancer compared with normal pancreatic tissue." (PMID 36932397, 2023). "EGR1 was highly expressed in pancreatic cancer rather than normal pancreatic tissues and correlated with poor prognosis and cancer metastasis." (PMID 36932397, 2023). "Importantly, together with an ongoing inflammatory response we observed the significant induction of early response genes Egr-1 and IER-5 in wasted pancreatic cancer patients (p<0.05)." (PMID 22721276, 2012). "In pancreatic cancer, whether EGR1 acts as a tumor promoter or tumor suppressor has not been determined." (PMID 36932397, 2023). "Effects of nicotine on the EGR-1 gene in pancreatic cancer cells has not been studied to date." (PMID 25260978, 2014).